CCR2 (C-C motif chemokine receptor 2)
Diseases named in the same sentence as CCR2 in open-access papers (continued):
Sharing a sentence is not in itself a finding about the gene and the disease.
tumor (continued). "Also, Chemokine (C-C motif) ligand 2 (CCL2)-CCR2 axis is important in involving immune cells in tumor progression." (PMID 40472038, 2025). "GBM expresses CCL2 and CCL7, which facilitate tumor recruitment by CCR2+ cells." (PMID 40514725, 2025). "Thus, the resulting CCL2 gradient activates CCR2-dependent signaling cascades that collectively foster a tumor-permissive niche." (PMID 41276817, 2025). "Furthermore, combination of CCR2 antagonism with anti-PD-1 therapy has been shown to lead to sensitization and enhanced tumour reduction in comparison to anti-PD-1 monotherapy." (PMID 40385641, 2025). "We hypothesized that plozalizumab in combination with checkpoint inhibition has the potential to block circulating myeloid-derived suppressor cells that overexpress CCR2 from trafficking to the tumor microenvironment." (PMID 41049010, 2025). "The tracer was found to specifically target and distribute in CCR2-positive cells in the tumor stroma, especially on macrophages, significantly enhancing the delivery efficiency of gemcitabine and effectively inhibiting tumor growth." (PMID 40725764, 2025). "Interestingly, we also observed reduced migration of Ccr2-/- monocytes towards tumor cell-derived supernatant from Ccl2KD cells, indicating an additional Ccl2-dependent mechanism." (PMID 39566333, 2025). "Our results revealed that the CCR2+ subset of tumor-associated macrophages (TAMs) plays a critical role in establishing an immunosuppressive TME post-iIRE treatment, thereby facilitating rapid tumor recurrence." (PMID 40700478, 2025). "Ccr2-deficient mice lacking monocyte precursors demonstrate incomplete depletion of TAMs in both spontaneous and transplanted tumour models, indicating the presence of a monocyte-independent TAM population." (PMID 40523200, 2025). "To confirm the inhibition of tumor growth associated with decreased chemokine expression in Ccn1‐KO tumor, we focused on CXC chemokines, including CXCL1, CXCL3, and CXCL5, which bind to CXCR2, as well as CCL2 and CCL7, which bind to CCR2." (PMID 40287974, 2025). "Also, F. nucleatum induced adipocyte lipolysis through CCL2 autocrine signaling, and that CCR2 inhibition also reversed this metabolic reprogramming, thereby reducing the energy supply to tumor cells." (PMID 41276817, 2025). "Inhibition of the CCL2/CCR2 axis, critical for inflammatory cell recruitment, may also reduce tumor-induced immunosuppression and activate anti-tumor immunity." (PMID 41011273, 2025). "For instance, CD62L/CD62L ligands, CCR2/CCL2, VEGF receptor R1/VEGF-A, and CX3CR1/CX3CL1 receptor-ligand pairs have been most prominently associated with the recruitment of monocytes to the tumor microenvironment." (PMID 41440002, 2025). "For example, tumor‐derived CSF‐1 recruits CCR2+ monocytes that differentiate into TAMs." (PMID 40904700, 2025). "Chrysotile induced a more profound immune tumor response than crocidolite in Bap1-mutant mice by upregulating CD39/CD73-adenosine and Ccl2/Ccr2 pathways and recruiting more M2 macrophages, which together contributed to an immunosuppressive tumor microenvironment." (PMID 38592450, 2024). "In addition, blocking specific chemokine and cytokine receptors such as CCR2, CCR4 or Il-6R can reduce the recruitment of tumor-associated macrophages (TAMs), myeloid-derived suppressor cells (MDSCs) or regulatory T cells (Tregs)." (PMID 38928238, 2024). "In addition, IL6 and CCR2 were among the top 10 most upregulated DEGs in HPV − tumor cells compared with HPV + tumor cells." (PMID 38468260, 2024). "Therefore, simultaneous blockade of IL6 and CCR2 appears to be a promising therapeutic approach for the treatment of HPV − tumors by augmenting the tumor-infiltrating NK cell population." (PMID 38468260, 2024). "This may result from the underexpression of CCL2 and CCR2, responsible for monocyte recruitment to tumor sites, and the reduced levels of IL4 and IL13, genes known to promote monocyte polarization into M2 macrophages." (PMID 38733987, 2024).
tumor (continued). "Moreover, EHF significantly recruited and activated tumor‐associated macrophages (TAMs) through the C‐C motif chemokine 2/C‐C chemokine receptor type 2 (CCL2/CCR2) axis, thereby remodeling the tumor microenvironment." (PMID 38741887, 2024). "However, CCR2-expressing monocytes/macrophages, particularly in tumor microenvironments, can be strongly immunosuppressive." (PMID 38542388, 2024). "In recent years, researchers have explored strategies using CCR2 antagonists to selectively attract suppressive monocytes and macrophages into the tumor, with the goal of altering the tumor microenvironment and enhancing the immune system’s ability to combat cancer." (PMID 38650924, 2024). "Also, the combination of CCR2 and CXCR2 inhibitors can interrupt the accumulation of CCR2+ TAMs and CXCR2+ tumor-associated neutrophils (TANs) in the TME and enhance the effectiveness of chemotherapy in treating PDAC." (PMID 38835055, 2024). "Radiation-induced activation of the STING/type I IFN pathway enhances tumor-suppressive inflammation by recruiting myeloid cells through the CCR2 pathway, and treatments targeting CCR2 have mitigated the immunosuppressive effects of radiotherapy and STING agonist strategies." (PMID 39168971, 2024). "Therefore, CCL2 will likely be crucial in recruiting the CCR2+ monocytic precursors of CD163+ TAMs to tumours, as reported for CCR2+ MDSCs." (PMID 38903497, 2024). "In addition, Ccl12 from both Mac1 and Mac2 subclusters interact with Ccr2 in M1 + NextA tumor monocytes." (PMID 39272209, 2024). "Additionally, CCR2 antagonists can reduce TAM tumor infiltration by blocking the macrophage chemokine receptor." (PMID 39290697, 2024). "Consistently, CSF-1– CSF-1 receptor (CSF-1R) axis blockade or macrophage recruitment blockade via C-C chemokine receptor type 2 (CCR2)-inhibition could restore immune response against tumor in cancer models." (PMID 38426089, 2024). "CCR2 is also expressed in tumor cells and possesses a pro-cancerogenic function." (PMID 39199602, 2024). "It reported that inhibition of CCL2/CCR2 axis could reduce tumor infiltration and stimulate T cell responses." (PMID 39707188, 2024). "Crucially, CCR2/5 are major chemotactic regulators of tumor-promoting macrophages at the tumor site, and blocking these receptors could impede tumor progression in experimental animal models." (PMID 39080077, 2024). "This is why developing a CCR2 antagonist is a strategy to improve anti-tumor immunity." (PMID 38542388, 2024). "A clinical phase 1 trial targeting the CCL2/CCR2 signaling axis showed positive results, with an objective tumor response occurring in 49% and local tumor control in 97% of patients treated with the CCR2 antagonist PF-04136309 in combination with FOLFIRINOX chemotherapy." (PMID 40458305, 2024). "Therefore, the use of CXCR2 inhibitors in combination with CCR2 inhibitors is recommended to reduce the overall suppressive myeloid cell count, thus fostering a more robust anti-tumor immune response in PDAC." (PMID 38167055, 2024). "Moreover, CCX872-B, another CCR2 antagonist, disrupts the CCL2/CCR2 signaling pathway, reducing monocyte recruitment and subsequent tumor-promoting inflammation." (PMID 39076996, 2024). "MI was induced in CCR2-diphtheria toxin receptor mice, which had depleted monocytes and showed decreased effects on tumor growth, decreased tumor Ly6Chi monocytes, and a decrease in the proportion of regulatory T cells, as well as an increased proportion of activated T cells (granzyme B+)." (PMID 38279150, 2024). "Given the multiple reports that have classified CCL2 expression as having a role in the accumulation of CCR2+ TAMs in the PDAC TME, which has been associated with a decreased prognosis, trials have been initiated to understand if blocking CCR2 enhances anti-tumor effects in PDAC." (PMID 38339310, 2024).
tumor (continued). "On the other hand, once these CCR2-positive immune cells are within the tumor microenvironment, they might contribute to tumor growth, metastasis, and immune evasion through their interaction with CCL2." (PMID 38755605, 2024). "Finally, it was confirmed in the patient-derived tumor xenograft (PDTX) model that its binding with CCR2 on the surface of tumor cells can promote CCR2b-B7-H3-CAR-T cells to penetrate the blood–brain barrier." (PMID 38443969, 2024). "In human breast tumors, inflammatory mononuclear cells (IMCs) are recruited by binding chemokine (C-C motif) ligand 2 (CCL2), which is synthesized by tumor and stromal cells, to chemokine receptor 2 (CCR2), which promotes neovascularization and tumor cell infiltration." (PMID 39544302, 2024). "Intriguingly, Ccr2 and Ccl2, two proteins that are preferentially expressed in tumor cells and are critical for cancer cell proliferation, were strongly downregulated, suggesting a potential mechanism through which I-BRD9 inhibits AML but not HEK293T cell growth." (PMID 38126767, 2024). "Within CLL tumor microenvironments, CCR2-expressing monocytes are highly immunosuppressive." (PMID 38111528, 2023). "Then, we investigated whether the TC microenvironment could recruit mast cells to the tumor stroma by chemotaxis by screening the chemokine receptors involved in mast cell migration, including CCR2, CCR5, CXCR1, CXCR2, CXCR4, and CXCR7." (PMID 37042867, 2023). "TAM recruitment by CCL2 and CCR2 is critical to tumour invasion and metastasis." (PMID 37965573, 2023). "Blocking CCR2 reduces the growth of xenograft tumours and the infiltration of monocytes." (PMID 35999359, 2023). "Mondini and colleagues confirmed that radiotherapy can promote the secretion of CCL2 by tumor cells and induce the accumulation of CCR2+ Tregs and CCR2-dependent macrophages which can produce TNF-α, then TNF-α induces Tregs activation and decreases the efficacy of radiotherapy." (PMID 36845095, 2023). "The Mon Fn1 cell population is characterized by inflammatory features, including increased expression of the chemokine receptors Ccr2 and Ccr1 facilitating cell recruitment, immune suppression and tumor-promoting factors such as galectins (Lgals3/9), and the NLRP3 inflammasome inhibitor Tmem176b." (PMID 37756565, 2023). "Furthermore, CCL2 in tumors and CCR2 on tumor-infiltrating monocytes were increased with combination anti-PD-1/CTLA-4 treatment." (PMID 37449205, 2023). "MDSCs navigate the tumor microenvironment through chemokine receptors 2 (CCR2); GBM tumors express two CCR2 ligands, CCL2 and CCL7, which cause the tumor to signal the infiltration of CCR2+ cells." (PMID 37275361, 2023). "Thus, the loss of CCL2 or CCR2 in the host resulted in decreased MDSC recruitment and tumor growth but increased lung metastases." (PMID 37208442, 2023). "In addition, suppression of CCR2 expression in tumor cells normalized tumor growth in EC-Gαs KO animals, indicating that tumor cells are the main effector of endothelial CCL2." (PMID 36374225, 2023). "Similarly, in a model of DEN + CCl4-induced fibrosis-HCC, disruption of the CCL2/CCR2 axis reduced tumor burden and pathological vascularization." (PMID 36845555, 2023). "CCR2 is also highly expressed in macrophages and regulates myeloid cell recruitment to tumor sites." (PMID 38022534, 2023). "For example, blocking CCL2/CCR2 restricts monocytes from entering the tumor." (PMID 36941614, 2023). "The CCL2/CCR2 axis has been shown to not only regulate the infiltration and activation of monocytes, T lymphocytes, and NK cells, but to directly mediate angiogenesis, promote tumor invasion, and metastasis." (PMID 36838599, 2023). "A caveat is that once bone marrow-derived macrophages enter the tumor, the expression of chemokine receptors may be downregulated, as has been shown in ovarian cancer, where CCR2 expression is regulated by tumor-derived TNF." (PMID 37822933, 2023).
tumor (continued). "Also, CCL2/CCR2 assists in the tumor-promoting inflammation and recruitment of the TAMs in the tumor sites." (PMID 38017494, 2023). "The CCL2/CCR2 axis plays a crucial role in the recruitment of monocytic cells to the tumor site." (PMID 37849753, 2023). "This silencing will then activate the release of C-C motif chemokine ligand 2 (CCL2) from tumor cells, allowing myeloid cell recruitment via their C-C chemokine receptor type 2 (CCR2), which in turn will promote the chemotaxis and chemokinesis of tumor cells, and therefore tumor cell invasiveness." (PMID 37583899, 2023). "In mouse models of NASH-HCC, CCR2 deficiency did not ameliorate tumor development suggesting alternative sources of TAMs or alternative recruitment pathways involved in fatty liver disease progression." (PMID 36845555, 2023). "The proportion of circulating monocytes was the same in tumor-free WT, Ccl2-/-, or Ccr2-/- mice." (PMID 37208442, 2023). "Additionally, it has been demonstrated that CCR2‐dependant tumor entrained neutrophils present in the pre‐metastatic lung, can inhibit the seeding of tumor cells and suppress the colonization of tumor cells in the lung." (PMID 38062888, 2023). "It has already been proved that CCR2 triggers the differentiation of circulating monocytes into TAMs in the tumor microenvironment and another receptor that is required for the recruitment, differentiation, and survival of macrophages is called colony-stimulating factor-1 receptor (CSF1R)." (PMID 36109471, 2023). "Additionally, a CCR2 antagonist has exhibited tumor-burden-reducing efficacy in animal models of adenoid cystic carcinoma of the salivary glands by reducing the number of infiltrated TAMs." (PMID 38033495, 2023). "Collagen I depletion in tumor tissue results in enhanced oncogenesis and increased expression of Cxcl5, which causes recruitment of myeloid-derived suppressor cells and suppression of CD8 + T cells in a CXCR2/CCR2-dependent manner." (PMID 36906534, 2023). "Patients with high expression of atypical chemokine receptor 2 (ACKR2) may bind and internalize CCL2 for intracellular degradation to limit tumor metastasis, thus leading to low recruitment of CCR2+ monocytes along with high recruitment of CCR2+ NK cells." (PMID 36880535, 2023). "Consistently, loss of endothelial CCL2 or tumor cell CCR2 normalized the reduced tumor growth seen in mice lacking endothelial CALCRL or Gs." (PMID 36374225, 2023). "Furthermore, immune checkpoint inhibitors-mediated blockade of CCR2 or CSF1R receptors can increase the efficacy of immune checkpoint therapy via the prevention of TAM infiltration into tumor." (PMID 36109471, 2023). "When the monocyte-depleting anti-CCR2 antibody MC-21 was injected after DIVA2, a temporary reduction in tumor growth was observed, suggesting that the immunosuppressive phenotype of the CCR2+ tumor-infiltrating monocytes is responsible for the failure of tumor specific T cells to eradicate tumors." (PMID 37849753, 2023). "To evaluate their tumor promoting capacity we depleted CCR2+ cells in a therapeutic tumor setting with the anti-CCR2 antibody MC-21 and hypothesized a decrease of tumor growth after depletion." (PMID 37849753, 2023). "Collectively, MDSCs infiltrated in the lung of 4T1 tumor-bearing mice may be associated with the formation of the pre-metastatic niche and lung metastasis, and CXCR2 and CCR2 might be involved in the recruitment of MDSCs." (PMID 37268941, 2023). "Finally, we show that the CSF1R/CCR2/TGF-β Ab inhibits monocyte recruitment in patient-specific vascularized tumor models." (PMID 38076998, 2023). "Interestingly, increases of CCR2+ macrophages and monocytes were also observed in tumor-free mice after GEM and combination of paclitaxel (PTX) and doxorubicin (DOX) treatment." (PMID 36976637, 2023).
tumor (continued). "Increased levels of CCR2 and its ligand CCL2 promote tumor growth, are associated with inflammation, advanced cancer, and predicts prognosis and recurrence due to their role in the tumor microenvironment." (PMID 37629186, 2023). "Thus, the CCL2/CCR2 axis appeared to play a dual role by promoting early tumor development (pro-tumor) but sustaining the growth and lung metastasis of BC cells (antitumor)." (PMID 37208442, 2023). "For example, CCL2 derived from tumor cells recruit CCR2+ myeloid cells; hence CCR2 antagonist could directly reduce TAM infiltration and improve the efficacy of ICB in murine GBM." (PMID 37731483, 2023). "CCR2 expressing monocytes are recruited along the CCL2 gradient to the peripheral tumor site." (PMID 37849753, 2023). "Moreover, CCR2+ monocytes recruited by tumor cells from blood lead to abundance of M2-like macrophages and exhaustion of CD8+ T cells by secreting CCL232." (PMID 37215452, 2023). "Tumor-derived C–C motif chemokine ligand 2 (CCL2) binds to CCR2+/Ly6Chi endothelial cells to increase vascular permeability and recruit inflammatory monocytes in a p38/MAPK-dependent manner, thereby promoting the extravasation and seeding of metastatic cancer cells." (PMID 36313280, 2022). "Thus, recent studies in the orthotopic Hepa1-6 HCC mouse model identify the CCL2/CCR2 axis as critical for HSPC recruitment to the spleen of tumor bearing mice, and establish its effective suppression by CCR2 antagonists." (PMID 36561751, 2022). "In addition, blockade of monocyte recruitment using CCL2/CCR2 inhibitors prevents MDSC accumulation in the tumor but has shown limited single-agent activity and requires combination with chemotherapeutic agents." (PMID 35179953, 2022). "In addition, it has recently been discovered that blocking CCR2 produced an anti-tumor immune response at the metastatic site, providing a new target for clinical treatment." (PMID 36348319, 2022). "A subpopulation of CCR2 (receptor for chemokine CCL2) expressing monocytes was recruited by metastatic tumor cells which enhanced the subsequent extravasation of the tumor cells through the targeted delivery of molecules such as vascular endothelial growth factor(VEGF)." (PMID 35962400, 2022). "The chemoattractant CCL2 molecule has been involved in several cancers for inducing MDSC/TAM tumor infiltration and targeting this chemokine with anti-CCL2 antibodies and/or inhibitors of its major ligand, CCR2, have improved tumor regression in pre-clinical models of several cancers." (PMID 36613562, 2022). "Therefore, we concluded that SBRT followed by αPD-1 treatment and a prolonged treatment course of CCR2/5i was the best treatment strategy among all therapies that had been tested thus far for this mouse model of orthotopically implanted KPC tumor." (PMID 35404390, 2022). "Bone marrow-derived CCR2+ MDSCs may affect the transport of T cells to the tumor site, supporting tumor growth." (PMID 35053426, 2022). "In mouse tumor models, CCR2 blockade depletes inflammatory resident monocytes and macrophages from the primary tumor and premetastatic liver, resulting in enhanced antitumor immunity, decreased tumor growth, and reduced metastasis." (PMID 35404390, 2022). "CCL2 binds to its cognate receptor CCR2 to mediate its tumor promoting effect." (PMID 35865534, 2022). "However, the CCL2/CCR2 pathway was described to allow the recruitment of adoptively transferred CD8 T cells within lymphoma murine tumors, and this was associated with tumor growth control." (PMID 36429101, 2022). "Other strategies to mitigate MDSCs recruitment to the tumor bed could by the blocking of MDSCs chemokine receptors, as it is the case of CCR2." (PMID 35211124, 2022). "In the tumor microenvironment, knockout of CCR2 or intervention with CCR2 antagonists can inhibit HCC tumor growth and metastasis by regulating the recruitment and polarization of tumor-associated macrophages (TAMs) and can improve survival in mouse HCC models." (PMID 35281057, 2022).